SSBP2 (single stranded DNA binding protein 2)
Synonyms: HSPC116; SOSS-B2
Tractability: PROTAC: ubiquitination databases record sites on it.
Gene: Protein-coding gene on chromosome 5 (81,412,804 to 81,752,038, reverse strand). Ensembl gene ENSG00000145687.
Subcellular location: Nucleus
Subcellular location (Human Protein Atlas): Nucleoplasm
Gene Ontology:
Molecular function: protein binding; single-stranded DNA binding; transcription coactivator activity
Biological process: positive regulation of transcription by RNA polymerase II; regulation of DNA-templated transcription
Cellular component: cytoplasm; nucleoplasm; nucleus
Genetic constraint (gnomAD): Loss-of-function variants: 6 observed, 20.96 expected, observed/expected ratio (o/e) 0.29, 90% interval 0.16 to 0.56. The upper end of that interval is the gene's LOEUF score, 0.56, which puts it in group 2 of 6, group 1 being the genes least tolerant of losing a copy. Missense variants: 149 observed, 197.38 expected, observed/expected ratio (o/e) 0.75, 90% interval 0.66 to 0.87. Synonymous variants: 73 observed, 66.49 expected, observed/expected ratio (o/e) 1.1, 90% interval 0.91 to 1.33.
Homologues: Orthologues: chimpanzee SSBP2 (100% identical), dog SSBP2 (100% identical), macaque SSBP2 (98% identical), mouse Ssbp2 (98% identical), rat Ssbp2 (93% identical), guinea pig SSBP2 (92% identical), pig SSBP2 (90% identical), zebrafish ssbp2b (84% identical), zebrafish ssbp2a (80% identical), tropical clawed frog ssbp2 (71% identical), Drosophila melanogaster Ssdp (63% identical), Caenorhabditis elegans sam-10 (37% identical), and 1 more. Paralogues in human: SSBP3 (82% identical), SSBP4 (73% identical).
Diseases named in the same sentence as SSBP2 in open-access papers:
SSBP2 is named in the same sentence as 40 diseases in open-access papers, as found by Europe PMC text mining. Sharing a sentence is not in itself a finding about the gene and the disease. The quoted sentences say what the papers report.
prostate carcinoma (6 papers, 2010 to 2022). A carcinoma that arises from epithelial cells of the prostate gland. "The loss of SSBP2 expression is associated with various types of malignancies, such as esophageal squamous cell carcinoma, prostate cancer, gallbladder cancer, and acute myeloid leukemia." (PMID 33339271, 2020). "Although increased SSBP2 expression was associated with shorter survival in glioblastoma, SSBP2 was also shown to inhibit the growth of prostate cancer cells and to act as a tumor suppressor in myeloid leukemias." (PMID 27780223, 2016). "Furthermore, hypermethylation of SSBP2 was closely associated with higher stages, and forced expression of SSBP2 inhibited prostate cancer cell proliferation in a colony formation assay and caused cell cycle arrest." (PMID 30541499, 2018). "SSBP2 functioned as a tumor suppressor in gall bladder cancer, esophageal squamous cell carcinoma, and prostate cancer." (PMID 32745119, 2020). "The role of SSBP2 has also been studied in several solid tumors including hepatocellular carcinoma, gallbladder cancer, esophageal squamous cell carcinoma, and prostate cancer." (PMID 32745119, 2020). "They further examined the SSBP2 expression pattern using immunohistochemistry and showed that SSBP2 was significantly downregulated in most of the primary prostate cancer tissues, compared with normal prostate tissues." (PMID 33339271, 2020). "Promoter hypermethylation of SSBP2 was observed in several solid tumors, including gall bladder cancer, esophageal squamous cell carcinoma, prostate cancer, ovarian cancer, and hepatocellular carcinoma." (PMID 32745119, 2020). "The majority of previous studies have suggested a tumor-suppressive role of SSBP2, which is silenced by promoter hypermethylation in most solid tumors, such as prostate cancer, esophageal squamous cell carcinoma, ovarian cancer, and gallbladder cancer." (PMID 30541499, 2018). "The majority of previous studies have suggested a tumor-suppressive role of SSBP2, which is silenced by promoter hypermethylation in several human malignancies, such as hematologic malignancies, prostate cancer, esophageal squamous cell carcinoma, ovarian cancer, and gallbladder cancer." (PMID 30541499, 2018). "Most studies have suggested a tumor suppressive role of SSBP2, which is silenced by promoter hypermethylation in several human tumors, including hematologic malignancies, prostate cancer, esophageal squamous cell carcinoma, ovarian cancer, and gallbladder cancer." (PMID 30541499, 2018). "SSBP2 is downregulated in several malignancies, such as esophageal squamous cell carcinoma, prostate cancer, and acute myeloid leukemia, and in previous studies, it has been speculated that promoter methylation may be the main mechanism of loss of SSBP2 expression." (PMID 33339271, 2020).
acute myelogenous leukemia (5 papers, 2010 to 2022). "The human SSBP2 gene was first found in leukemic blasts and is known to be deleted and translocated in acute myelogenous leukemia and myelodysplasia." (PMID 35204577, 2022). "Although SSBP2 is a well-known candidate tumor suppressor gene in acute myelogenous leukemia, the role of SSBP2 as a tumor promoter vs. a tumor suppressor in solid organ tumors is still controversial." (PMID 30541499, 2018). "The human single stranded DNA binding protein 2 (SSBP2) gene was first identified in primary leukemic blasts and was found to be translocated and deleted in myelodysplasia and acute myelogenous leukemia (AML)." (PMID 33339271, 2020).
esophageal squamous cell carcinoma (5 papers, 2018 to 2022). Esophageal squamous cell carcinoma (ESCC) is a type of esophageal carcinoma (EC) that can affect any part of the esophagus, but is usually located in the upper or middle third. "For example, SSBP2 decreased the colony-forming ability of esophageal squamous cell carcinoma cells through inhibiting Wnt signaling pathway." (PMID 35412941, 2022). "SSBP2 was shown to play a tumor-suppressive role in esophageal squamous cell carcinoma via inhibition of the Wnt signaling pathway." (PMID 33339271, 2020).
hepatocellular carcinoma (5 papers, 2018 to 2024). A malignant tumor that arises from hepatocytes. "SSBP2-positive hepatocellular carcinomas were significantly associated with aggressive phenotypes and poor clinical outcome." (PMID 30541499, 2018). "Most studies, except for a recent report on hepatocellular carcinoma, have reported SSBP2 to have tumor suppressive action." (PMID 32745119, 2020). "The minority of hepatocellular carcinomas expressed SSBP2 by immunohistochemistry, whereas normal hepatocytes were negative." (PMID 30541499, 2018). "However, some studies have indicated that overexpression of SSBP2 can exert oncogenic effects which correlated with adverse clinical outcomes in hepatocellular carcinoma and glioblastoma." (PMID 38866828, 2024). "However, a few studies have suggested that SSBP2 is a tumor promoter in glioblastoma and hepatocellular carcinoma." (PMID 35204577, 2022). "Some authors have reported that SSBP2 may play a role in promoting cancer progression because its expression was found to be upregulated in some tumors, including glioblastoma and hepatocellular carcinoma." (PMID 35204577, 2022). "We investigated the clinicopathologic significance of SSBP2 expression in hepatocellular carcinoma." (PMID 30541499, 2018). "In this study, we investigated the immunohistochemical expression of SSBP2 in normal liver parenchyma and hepatocellular carcinoma tissues with corresponding adjacent non-neoplastic tissues." (PMID 30541499, 2018). "In addition, the SSBP2 (single-stranded DNA binding protein 2)–FER fusion and the MAN2A1 (mannosidase alpha class 2A member 1)–FER fusion have also been identified in leukemia and hepatocellular carcinoma patients, respectively." (PMID 37196766, 2023).
leukemia (5 papers, 2010 to 2023). A malignant (clonal) hematologic disorder, involving hematopoietic stem cells and characterized by the presence of primitive or atypical myeloid or lymphoid cells in the bone marrow and the blood. "Two other proteins (RAD50 and SSBP2) were very low in infant leukemia (<2 years), but then relatively similar across other age subsets with a tendency to drop again after the age of 60 years." (PMID 36982537, 2023). "Sequence-specific single-stranded DNA binding protein 2 (SSBP2) was originally isolated as a candidate leukemia suppressor gene from chromosome 5q13.3 that is disrupted in the human acute myelogenous leukemia (AML) cell line ML3." (PMID 20540776, 2010). "CD5 positivity in DLBCL was frequently associated with lack of SSBP2 expression, a tumor suppressor protein for lymphoma and leukemia." (PMID 25760242, 2015).
myeloid leukemia (4 papers, 2016 to 2022). A clonal proliferation of myeloid cells and their precursors in the bone marrow, peripheral blood, and spleen. "The human single-stranded DNA binding protein 2 (SSBP2) gene was identified as a candidate tumor suppressor of myeloid leukemia from a critical region of loss in chromosome 5q14.1." (PMID 30541499, 2018). "Several studies have demonstrated that SSBP2 is a tumor suppressor in solid tumors and myeloid leukemia." (PMID 35204577, 2022). "The role of SSBP2 in human malignancies has been studied in several solid tumors and myeloid leukemia." (PMID 35204577, 2022). "The single-stranded DNA binding protein 2 (SSBP2) gene, which is located at chromosome 5q14.1, was previously identified as a candidate tumor suppressor in myeloid leukemia patients." (PMID 35204577, 2022). "Single-stranded DNA binding protein 2 (SSBP2) is known to be a candidate tumor suppressor in patients with myeloid leukemia located at chromosome 5q14." (PMID 32745119, 2020).
ovarian carcinoma (4 papers, 2018 to 2022). A malignant neoplasm originating from the surface ovarian epithelium. "The results revealed that hypermethylation of SSBP2 was observed in 3 out of 33 (9%) ovarian cancer samples; however, there was no statistical significance." (PMID 30541499, 2018). "Furthermore, in ovarian cancer, SSBP2 methylation was found in 9% of tumor cases, whereas no cases showed methylation of the SSBP2 promoter in normal tissues." (PMID 33339271, 2020).
Cholecystitis (3 papers, 2018 to 2022). The presence of inflammatory changes in the gallbladder. "This study revealed that promoter methylation statuses of SSBP2 (p = 0.01) were significantly different in patients with gallbladder cancer when compared to those of patients with cholecystitis." (PMID 33339271, 2020).
glioblastoma (3 papers, 2016 to 2022). The most malignant astrocytic tumor (WHO grade IV). "Increased expression of SSBP2 was significantly associated with poor overall survival among glioblastoma patients." (PMID 30541499, 2018). "However, an oncogenic role of SSBP2 has been suggested in glioblastoma patients." (PMID 30541499, 2018).
breast carcinoma (2 papers, 2022). "SNP rs413472 (5q14.1) is located in the SSBP2 gene which has previously been implicated in breast cancer (p = 4.00 × 10−5) in Indonesian women." (PMID 35414113, 2022). "During survival analysis, loss of nuclear SSBP2 expression was associated with poorer OS in patients with breast carcinoma." (PMID 35204577, 2022). "In our study, we found that loss of nuclear SSBP2 expression was correlated with larger tumor size, higher histological grade, and higher pT stage, which indicates that it may be involved in breast cancer progression." (PMID 35204577, 2022). "The exact function of nuclear SSBP2 expression and its potential as a novel biomarker for breast carcinoma should be further evaluated in future studies." (PMID 35204577, 2022). "Our results imply that nuclear SSBP2 expression may play a role as a tumor suppressor in breast carcinoma." (PMID 35204577, 2022). "There is also no study that supports the exact role of SSBP2 expression in breast cancer until now." (PMID 35204577, 2022). "The role of SSBP2 in human breast cancer has not yet been reported." (PMID 35204577, 2022).
colorectal adenocarcinoma (2 papers, 2020 to 2022). The most common type of colorectal carcinoma. "In conclusion, we showed that SSBP2 expression was significantly decreased in colorectal adenocarcinoma and metastatic carcinoma tissues and was associated with poor prognostic factors." (PMID 33339271, 2020). "Overall, a loss of nuclear SSBP2 expression was observed in 134 (34.3%) primary colorectal adenocarcinoma and 100 (76.3%) metastatic carcinoma tissues, while all normal colonic mucosa and adenoma tissues showed a positive SSBP2 expression." (PMID 33339271, 2020).
gastric adenocarcinoma (2 papers, 2020 to 2022). "Complete loss of nuclear expression of SSBP2 was correlated with a high pT category and lymph node metastasis, suggesting an association with progression of the gastric adenocarcinoma." (PMID 32745119, 2020). "In this study, we investigated the expression of SSBP2 and its prognostic role in gastric adenocarcinoma." (PMID 32745119, 2020). "In conclusion, we investigated the pattern of SSBP2 expression through immunohistochemistry, as well as its clinicopathological significance in patients with gastric adenocarcinoma." (PMID 32745119, 2020). "Correlation between single-stranded DNA binding protein 2 expression and molecular characteristics in patients with gastric adenocarcinoma (n = 539)." (PMID 32745119, 2020). "Correlation between single-stranded DNA binding protein 2 expression and clinicopathological features in patients with gastric adenocarcinoma (n = 539)." (PMID 32745119, 2020).
lymph node metastasis (2 papers, 2020 to 2022). "The univariate Cox regression analysis for OS showed that histological grade (p = 0.002), pT stage (p = 0.01), ER status (p = 0.009), lymph node metastasis (p = 0.002), and SSBP2 expression (p = 0.016) were significantly associated with OS." (PMID 35204577, 2022).
adenoma (1 paper, 2020). A neoplasm arising from the epithelium. "An SSBP2 expression loss was found in 34.3% of primary adenocarcinoma and 76.3% of metastatic adenocarcinoma tissues; however, no expression loss was found in matched normal colonic mucosa and adenoma cases." (PMID 33339271, 2020). "SSBP2 nuclear expression was evaluated immunohistochemically in 48 normal colonic mucosae, 47 adenomas, 391 primary adenocarcinomas, and 131 metastatic carcinoma tissue samples." (PMID 33339271, 2020). "A diffuse nuclear SSBP2 expression was detected in all normal colonic mucosa and adenoma samples." (PMID 33339271, 2020).
B-cell lymphomas (1 paper, 2015). "In mouse models, loss of SSBP2 resulted in hypoplastic hematopoietic tissues and impaired hematopoiesis and was associated with shortened lifespan and greater susceptibility to B-cell lymphomas." (PMID 25760242, 2015).
basal cell carcinoma (1 paper, 2023). A carcinoma involving the basal cells. "In this study, the expression level and clinicopathological significance of SSBP2 in squamous cell carcinoma (SCC) and basal cell carcinoma (BCC) were evaluated." (PMID 37509458, 2023).
colorectal cancer (1 paper, 2020). A primary or metastatic malignant neoplasm that affects the colon or rectum. "Nuclear SSBP2 expression loss was significantly observed in colorectal carcinoma and metastatic carcinoma tissues, being associated with poor prognostic factors." (PMID 33339271, 2020). "If the same results are gathered in more groups in the future and target therapy studies for SSBP2 are progressed, it will be a cornerstone for the opening of a new treatment for colorectal cancer, which remains a challenge." (PMID 33339271, 2020). "SSBP2 acts as a tumor suppressor and may be used as a prognostic biomarker in colorectal cancer." (PMID 33339271, 2020). "However, the correlation between SSBP2 expression and colorectal cancer (CRC) prognosis remains unclear." (PMID 33339271, 2020).
Flavivirus Infections (1 paper, 2020). Infections with viruses of the genus FLAVIVIRUS, family FLAVIVIRIDAE. "Furthermore, down-regulation of SSBP2 expression, a protein notably involved in RNA transcription, could be linked to the control of gene expression during flavivirus infection." (PMID 32374750, 2020).
gastric cancer (1 paper, 2020). A primary or metastatic malignant neoplasm involving the stomach. "Further studies are needed to confirm the association between molecular subtypes and SSBP2, and these studies will also help these studies will help to understand the role of SSBP2 and its effect on carcinogenesis and cancer progression in gastric cancer." (PMID 32745119, 2020). "In the 539 patients with gastric carcinomas, loss of SSBP2 expression was associated with shorter RFS and OS (P = 0.008 and P = 0.072, respectively)." (PMID 32745119, 2020). "Therefore, we tried to identify the expression of SSBP2 through immunohistochemistry in gastric cancer and analyzed the association of expression and prognosis." (PMID 32745119, 2020). "In the MSS and EBV negative gastric cancer group, Kaplan-Meier survival curves also showed that a loss of nuclear SSBP2 expression was associated with shorter RFS and OS (P = 0.002 and P = 0.087, respectively)." (PMID 32745119, 2020). "We investigated SSBP2 expression and its clinicopathological significance in gastric cancer." (PMID 32745119, 2020). "SSBP2 expression was examined by immunohistochemistry in 539 gastric cancer sections." (PMID 32745119, 2020). "The prognostic impact of SSBP2 expression in gastric cancer, determined by immunohistochemistry, has not been reported." (PMID 32745119, 2020). "However, no studies are available regarding the expression of SSBP2 in gastric cancer." (PMID 32745119, 2020). "The association of molecular alterations according to the molecular subtypes of gastric cancer, such as MLH1 hypermethylation, and promoter methylation of SSBP2 is not yet known." (PMID 32745119, 2020).
invasive breast carcinoma (1 paper, 2022). A carcinoma that infiltrates the breast parenchyma. "Loss of nuclear SSBP2 expression was found in 61 cases of invasive breast carcinoma." (PMID 35204577, 2022). "In addition, loss of nuclear SSBP2 expression was associated with poorer OS in patients with invasive breast carcinoma." (PMID 35204577, 2022). "In this study, we investigated the expression of SSBP2 by immunohistochemistry in invasive breast carcinoma tissues, analyzed the associations between SSBP2 expression and various clinicopathological characteristics, and assessed whether SSBP2 is a prognostic factor for patient survival." (PMID 35204577, 2022). "In conclusion, we investigated the clinicopathological significance of nuclear SSBP2 expression in 491 invasive breast carcinomas." (PMID 35204577, 2022). "In the present study, we evaluated nuclear SSBP2 expression in 491 cases of invasive breast carcinoma and investigated the correlations between nuclear SSBP2 expression and clinicopathological characteristics and patient survival." (PMID 35204577, 2022). "SSBP2 acts as a tumor suppressor in invasive breast carcinoma and may be used as a prognostic biomarker." (PMID 35204577, 2022). "Of 491 invasive breast carcinoma cases, 61 cases (12.4%) showed negative nuclear SSBP2 expression and 430 cases (87.6%) showed positive nuclear SSBP2 expression on IHC staining." (PMID 35204577, 2022). "However, the role of SSBP2 expression in invasive breast carcinoma has not been reported." (PMID 35204577, 2022).
lupus nephritis (1 paper, 2025). Glomerulonephritis in the context of systemic lupus erythematosus. "This work represents one of the earliest investigations into the dysregulated expression of the TRIM8-associated non-coding RNA network—encompassing lnc-SSBP2-1:1 and hsa-miR-126-5p—in lupus nephritis." (PMID 41194165, 2025).
metastatic carcinoma (1 paper, 2020). A carcinoma which has spread from the original site of growth to another anatomic site. "SSBP2 expression loss was observed in 131 (34.3%) primary adenocarcinoma and 100 (76.3%) metastatic carcinoma samples." (PMID 33339271, 2020). "SSBP2 expression was significantly decreased in primary adenocarcinoma and metastatic carcinoma tissues (all, p < 0.001)." (PMID 33339271, 2020).